YTHDF2 (YTH N6-methyladenosine RNA binding protein F2)
Diseases named in the same sentence as YTHDF2 in open-access papers (continued):
Sharing a sentence is not in itself a finding about the gene and the disease.
cholangiocarcinoma (12 papers, 2020 to 2025). A carcinoma that arises from the intrahepatic biliary tree (intrahepatic cholangiocarcinoma) or from the junction, or adjacent to the junction, of the right and left hepatic ducts (hilar cholangiocarcinoma). "Recent evidence showed that METTL3 promotes cholangiocarcinoma progression by YTHDF2-mediated IFIT2 mRNA degradation." (PMID 38267969, 2024). "Similarly, METTL14 facilitates the degradation of Siah2 mRNA through m6A modification and YTHDF2-mediated decay in cholangiocarcinoma (CCA)." (PMID 40034695, 2025). "In cholangiocarcinoma (CCA), METTL14 increases m6A modifications in the 3′UTR region of Siah2 mRNA, leading to its degradation via a YTHDF2‐dependent mechanism." (PMID 39802639, 2025). "This study not only elucidates the complex interplay between LINC00511, YTHDF2, and SOX2 but also proposes potential therapeutic targets within this regulatory axis for cholangiocarcinoma treatment." (PMID 39445001, 2024). "The ubiquitination of PD-L1 in cholangiocarcinoma (CCA) is diminished by METTL14 through YTHDF2-mediated inhibition of the RING E3 ubiquitin ligase Siah2, and the deprivation of Siah2 represses T-cell expansion and toxicity by maintaining tumour PD-L1 expression." (PMID 36859310, 2023). "YTHDF2 expression was not expressed substantially between cholangiocarcinoma, lung squamous cell carcinoma, READ (rectum adenocarcinoma), and thyroid carcinoma tissues and adjacent normal tissues." (PMID 32986017, 2020). "Similar to NSCLC, in cholangiocarcinoma (CCA), METTL14 binds Siah2 mRNA in the 3′-UTR region and triggers m6A modification, promoting its degradation in a YTHDF2-dependent manner." (PMID 36960074, 2023). "A time‐course following treatment with actinomycin D showed that siRNA‐mediated knockdown of YTHDF2 specifically reduced the stability of SOX2 mRNA in CCLP‐1 cells with little effect on HIBEC, thus indicating a CCA‐specific dependency where YTHDF2 supports cholangiocarcinoma cells." (PMID 39445001, 2024).
Obesity (12 papers, 2020 to 2025). Accumulation of substantial excess body fat. "Enrichment of A. muciniphila leads to generate more indole‐3‐lactic acid (ILA) to upregulate the expression of 12α‐hydroxylase (CYP8B1) via fat mass and obesity‐associated protein (FTO)/ N6‐methyladenosine (m6A)/YTHDF2 manner, thereby facilitating cholesterol converts to cholic acid (CA)." (PMID 39888270, 2025). "Furthermore, in human cohorts, the study found that the writers WTAP and VIRMA, the eraser ALKBH5, and reader proteins such as YTHDF1, YTHDF2, and YTHDC1 are associated with obesity by comparing gene expression of m6A regulators in adipose tissue between individuals with obesity and lean controls." (PMID 40428320, 2025). "Suppressed levels of readers/erasers such as YTHDF2 may lead to a hypo-metabolic state in obesity." (PMID 38392966, 2024). "Consequently, YTHDF2 could function by regulating the expression of target genes to influence the development of various diseases, including DM, obesity, and MAFLD." (PMID 38392966, 2024). "Moreover, m6A-YTHDF2-FTO signaling way might be crucial for the development of obesity, m6A—binding protein YTHDF2 can methylate mRNAs of cyclin A2 (CCNA2) and cyclin dependent kinase 2 (CDK2), and then reduce their protein expression to prolong cell cycle progression and suppress adipogenesis." (PMID 32110378, 2020).
cardiac hypertrophy (11 papers, 2021 to 2025). "Mechanistically, YTHDF2 recognizes the m6A site on Myh7 (beta-myosin heavy chain) mRNA, promoting its degradation and thereby alleviating cardiac hypertrophy." (PMID 40005339, 2025). "Conversely, lncRNA MIAT-induced YTHDF2 high expression stimulates cardiac hypertrophy by downregulating CPT-1a levels in the PPARα pathway." (PMID 36999016, 2023). "Then we found that the Ythdf2 (readers) was highly expressed and there was a significant difference in cardiac hypertrophy model (logFC = 1.114; P = 0.00057)." (PMID 35383152, 2022). "We found that lncRNA MIAT mRNA level, and m6A RNA methylation reading protein Ythdf2 mRNA and protein levels, were significantly increased in the cardiac hypertrophy model both in vivo and vitro." (PMID 35383152, 2022). "RT-qPCR assay revealed that the promotive role of AngII on H9c2 cardiac hypertrophy phenotype was enhanced by Ythdf2 overexpression." (PMID 35383152, 2022). "Perhaps the most remarkable finding of our research was the demonstration that MIAT plays an important regulatory role in cardiac hypertrophy through the m6A methylated reading protein Ythdf2 in vitro cellular model." (PMID 35383152, 2022). "RT-qPCR assay showed that the promotive effect of AngII on cardiac hypertrophy phenotype was suppressed by Ythdf2 knockdown." (PMID 35383152, 2022). "The results provided a new understanding of the MIAT and m6A RNA methylation reading protein, Ythdf2, function and mechanism in cardiac hypertrophy and highlighted the potential therapeutic benefits in the heart." (PMID 35383152, 2022). "Knockdown of Myh7 or deletion of the YTH domain of YTHDF2 reversed the protective effects of YTHDF2 on cardiac hypertrophy." (PMID 34266473, 2021). "This study highlights the functional importance of YTHDF2-dependent cardiac m6A mRNA regulation during cardiac hypertrophy, and provides a novel mechanistic insight into the therapeutic mechanisms of YTHDF2." (PMID 34266473, 2021). "In this study, we find that YTHDF2 suppresses cardiac hypertrophy through regulating Myh7 mRNA decoy in vitro using the primary mice cardiomyocytes stimulated with ISO or PHE, and in vivo using TAC mouse model." (PMID 34266473, 2021). "Overall, our results indicate that the m6A Reader YTHDF2 suppresses cardiac hypertrophy via Myh7 mRNA decoy in an m6A-dependent manner." (PMID 34266473, 2021). "In conclusion, out study explores the role of YTHDF family proteins during HF development, and indicates YTHDF2 suppresses cardiac hypertrophy and HF via Myh7 mRNA decoy in an m6A-dependent manner." (PMID 34266473, 2021). "Collectively, these results indicate that YTHDF2 overexpression alleviates cardiac hypertrophy in vivo." (PMID 34266473, 2021). "Moreover, YTHDF2 protein levels increased in cell and animal models of cardiac hypertrophy stimulated by isoproterenol or phenylephrine." (PMID 40005339, 2025). "It is unclear whether Ythdf2 is presented in cardiovascular diseases and affects cardiac hypertrophy." (PMID 35383152, 2022). "Finally, we found that MIAT was a necessary regulator of cardiac hypertrophy due to its regulation of the Ythdf2/PPARα/CPT-1a axis." (PMID 35383152, 2022). "In this study, we demonstrated that MIAT influenced AngII-induced cardiac hypertrophy by regulating the expression of a key m6A RNA methylation enzyme, Ythdf2, and may influence its downstream target genes PPARα/CPT-1a." (PMID 35383152, 2022). "As anticipated, Ythdf2 functioned as a downstream of MIAT in cardiac hypertrophy." (PMID 35383152, 2022). "We found that MIAT and Ythdf2 were significantly increased during cardiac hypertrophy." (PMID 35383152, 2022). "Furthermore, previous studies have shown m6A modification promoted YTHDF2 protein expression through enhancing Ythdf2 mRNA stability in cardiac hypertrophy." (PMID 35953789, 2022).
cardiac hypertrophy (continued). "Furthermore, the cells transfected with Ythdf2 plasmid had increased mRNA and protein expression of cardiac hypertrophy markers ANP, BNP, and β-MHC, whereas PPARα and CPT-1a were significantly decreased relative to control groups." (PMID 35383152, 2022). "MIAT or Ythdf2 overexpression aggravated cardiac hypertrophy, and vice versa." (PMID 35383152, 2022). "Similarly, knockdown of Ythdf2 decreased cardiac hypertrophy markers ANP, BNP, and β-MHC, whereas PPARα and CPT-1a mRNA and protein levels were increased." (PMID 35383152, 2022). "However, ISO or PHE stimulation significantly increased YTHDF2 protein interacting with Myh7 (beta-myosin heavy chain) mRNA, an important cardiac hypertrophy marker, in an m6A-dependent manner." (PMID 34266473, 2021). "Furthermore, we found that YTHDF2 suppresses cardiac hypertrophy via Myh7 mRNA decoy in an m6A-dependent manner." (PMID 34266473, 2021). "Thus, hiPSC (human induced pluripotent derived stem cell)-differentiated cardiomyocytes should be used to further uncover the regulatory mechanism of YTHDF2 on human cardiac hypertrophy." (PMID 34266473, 2021). "Furthermore, YTHDF2 protein interacts with Myh7 (beta-myosin heavy chain) mRNA, an important cardiac hypertrophy marker, to induce Myh7 mRNA decoy in an m6A-dependent manner, thereby inhibiting HF development." (PMID 34266473, 2021). "Furthermore, consistent with the in vitro results, YTHDF2 mRNA and protein expression level was also significantly increased in the mice with cardiac hypertrophy induced by TAC." (PMID 34266473, 2021). "Next, we further explored whether the RNA binding ability of YTHDF2 is involved in YTHDF2 alleviating cardiac hypertrophy." (PMID 34266473, 2021). "Moreover, MYH7, a marker of cardiac hypertrophy, is also a target of YTHDF2." (PMID 37884527, 2023). "Several m6A “readers” might impede cardiac hypertrophy such as YTHDF2 and IGF2BP2." (PMID 35571209, 2022). "Furthermore, we discovered that Ythdf2 function was a downstream of MIAT in cardiac hypertrophy." (PMID 35383152, 2022). "YTHDF2 overexpression could efficiently alleviate cardiac hypertrophy." (PMID 34266473, 2021). "Furthermore, we detected whether YTHDF2 interacts with the mRNAs of cardiac hypertrophy makers, including ANP (atrial Natriuretic Peptide), BNP (brain natriuretic peptide), and MYH7 by RIP." (PMID 34266473, 2021). "Besides regulating mRNA decoy, whether the protective effect of YTHDF2 on cardiac hypertrophy and HF also related to these proteins requires further investigation in the following studies." (PMID 34266473, 2021). "The mice were injected with AAV9 viral particles carrying YTHDF2 (AAV-YTHDF2) through tail intravenous injection, or control AAV for 3 weeks, and the mice were later subjected to TAC to induce cardiac hypertrophy." (PMID 34266473, 2021). "Successful establishment of the cardiac hypertrophy model was confirmed by an obviously increased protein expression level of ANP, BNP, β-MHC and Ythdf2 in western blot and a clearly increased relative mRNA expression level of ANP, BNP, β-MHC, Ythdf2, and MIAT in RT-qPCR." (PMID 35383152, 2022). "To explore the mechanism of Ythdf2 in cardiac hypertrophy, we investigated whether Ythdf2 and CPT-1a actually interacted, which may affect the cardiac hypertrophy in H9c2 cells." (PMID 35383152, 2022). "To explore the mechanism of MIAT in cardiac hypertrophy, we first investigated whether MIAT and Ythdf2 actually interacted." (PMID 35383152, 2022). "Similarly, in cardiomyocytes, Ythdf2 alleviates cardiac hypertrophy by modulating Myh7 mRNA stability, rather than mRNA transition, highlighting a context-specific role of Ythdf2." (PMID 40824213, 2025). "The piRNA CHAPIR is identified as the upstream of METTL3.331CHAPIR regulates cardiac hypertrophy by interacting with METTL3 and inhibiting its methylase activity, leading to the hypomethylation of the ADP-ribosyltransferase Parp10 mRNA and the inhibition of YTHDF2-mediated degradation." (PMID 37884527, 2023).
cardiac hypertrophy (continued). "Furthermore, we found that knockdown of MYH7 significantly inhibited ISO or PHE-induced myocardial hypertrophy, and overexpression of YTHDF2 did not further alleviate myocardial hypertrophy." (PMID 34266473, 2021). "But, ISO stimulation did not affect the interaction of YTHDF2 and MYH7, suggesting YTHDF2 may be not affect cardiac hypertrophy by interacting with MYH7." (PMID 34266473, 2021).
clear cell renal cell carcinoma (10 papers, 2020 to 2025). "Our study delved into a novel mechanism through which ALKBH5 facilitated the transcription of MANF in clear cell renal cell carcinoma via a YTHDF2-dependent regulatory manner." (PMID 40603319, 2025). "Previous research verified that YTHDF2 has the ability to control the expression of circPOLR2A in a manner involving m6A modification in clear renal cell carcinoma." (PMID 38641828, 2024). "HDAC2 downregulated expression of the m6A reader, YTHDF2, by modulating clear cell renal cell carcinoma sensitivity to sunitinib therapy." (PMID 37691948, 2023). "Among clear cell renal cell carcinoma, YTHDF2 expression was demonstrated to be related with the immune infiltration of NEUs." (PMID 38049811, 2023). "Previous research has indicated that FTO promotes PDK1 expression by preventing the YTHDF2‐induced degradation of PDK1 mRNA via an m6A‐dependent mechanism, thereby facilitating the proliferation and migration of clear cell renal cell carcinoma." (PMID 39625183, 2024). "In addition, high YTHDF2 transcription was associated with a higher survival rate and increased tumor-infiltrating lymphocytes in clear cell renal cell carcinoma and NSCLC patients, suggesting the antitumor function of YTHDF2." (PMID 36017491, 2022).
non-small cell lung carcinoma (10 papers, 2021 to 2025). A group of at least three distinct histological types of lung cancer, including non-small cell squamous cell carcinoma, adenocarcinoma, and large cell carcinoma. "According to a recent study, YTHDF1 and YTHDF2 induced inflammation in the TIME in non-small-cell lung cancer." (PMID 36091006, 2022). "However, another study found that YTHDF2 overexpression inhibits non-small cell lung cancer (NSCLC) cell growth and invasion by promoting a decrease in yes-associated protein (YAP) mRNA in NSCLC cells." (PMID 35518355, 2022). "In non-small-cell lung cancer with high expressions of YTHDF1 and YTHDF2, the densities of four subsets of tumor-infiltrating lymphocytes (TILs; PD-1+, CD8+, Foxp3+, and CD45RO+) were significantly higher." (PMID 34956201, 2021). "For instance, in non-small cell lung cancer (NSCLC), YTHDF3 preferentially binds to the m6A sites on YAP pre-mRNA, while YTHDF1 and YTHDF2 competitively bind to respectively promote YAP translation or degradation, ultimately determining YAP protein levels and influencing tumor progression." (PMID 40384875, 2025).
systemic lupus erythematosus (9 papers, 2020 to 2025). An autoimmune multi-organ disease typically associated with vasculopathy and autoantibody production. "Decreased mRNA expression of YTHDF2 was found in patients with systemic lupus erythematosus and rheumatoid arthritis (RA) compared with controls, and YTHDF2 mRNA level in peripheral blood was a risk factor for RA by logistic regression analysis." (PMID 36072379, 2022). "The first available data were focused on the mRNA expression of m6A writers (METTL3, METTL14, and WTAP), erasers (FTO and ALKBH5) and readers (YTHDF2) in peripheral blood mononuclear cells (PBMCs) from lupus affected patients." (PMID 33807762, 2021). "Zhao's98 research revealed that circARs down‐regulate YTHDF2 via the A20/NF‐κB axis, promoting systemic lupus erythematosus (SLE)." (PMID 39135292, 2024). "Indeed, YTHDF2 expression was decreased in systemic lupus erythematosus (SLE) and type I diabetes as compared with healthy controls." (PMID 41224760, 2025). "In a recent study of systemic lupus erythematosus (SLE), the circGARS/miR-19a signaling pathway was shown to regulate the expression of YTHDF2 to alter the activation of the immune response, which was mediated by tumor necrosis factor alpha-induced protein 3 (TNFAIP3)." (PMID 36810108, 2023). "Likewise, EGFR, YTHDF2 also regulate the MAPK and NF-kB signalling in systemic lupus erythematosus (SLE)." (PMID 34833061, 2021).
Sepsis (8 papers, 2020 to 2025). Sepsis is defined as life-threatening organ dysfunction caused by a dysregulated host response to infection. "N6-methyladenosine writer METTL3 can also accelerate the sepsis-induced myocardial injury by m6A modification of SLC7A11 via YTHDF2 pathway." (PMID 40356926, 2025). "Trials have demonstrated a substantial correlation between m6A regulators including ALKBH5, HNRNPC, KIAA1429, WTAP, and YTHDF2 and 28-day cumulative mortality in sepsis patients." (PMID 38112620, 2023). "All of these results together confirmed the m6A reader protein YTHDF2 mediated the GPX4mRNA degraded and then lead to ferroptosis of alveolar epithelial cells in sepsis acute lung injury." (PMID 35637949, 2022). "The m6A modified SLC7A11 mRNA was recognized by YTHDF2, which promoted the decay of SLC7A11 mRNA, consequently up-regulating ferroptosis in sepsis-induced myocardial injury." (PMID 39234245, 2024). "Likewise, YTHDF2 recognizes METTL3-mediated m6A modification of SLC7A11 mRNA and promotes the degradation of SLC7A11 mRNA, ultimately leading to ferroptosis in sepsis-induced myocardial injury." (PMID 38112620, 2023).
colon carcinoma (7 papers, 2020 to 2025). "For instance, in colon cancer, downregulation of m6A levels reduces YTHDF2-dependent mRNA degradation, leading to increased expression of its target gene, KIF26B, and facilitating colon cancer progression and metastasis." (PMID 38576024, 2024).
endometrial cancer (7 papers, 2019 to 2025). Primary or metastatic malignant neoplasm involving the endometrium (mucous membrane that lines the endometrial cavity). "In endometrial cancers, the knockdown of YTHDF2, a ‘reader’ protein that acts to promote the decay of its target mRNAs, can impede the decay of mTORC2, thus activating the AKT pathway, which is also known to be triggered in EMs." (PMID 33232273, 2020). "By contrast, in endometrial cancer, METTL3 safeguards NLRC5 via a YTHDF2-dependent mechanism, maintaining MHC-I transcriptional programs and associating with greater CD8+ T-cell presence and tumor control." (PMID 41280938, 2025). "Likewise, in endometrial cancer, METTL3 contributes to the decay of transcripts such as PHLPP2 and mTORC2 via YTHDF2, inhibiting cancer cell proliferation." (PMID 38966069, 2024). "Similarly, a recent study demonstrated that both of YTHDF1 and YTHDF2 were involved in regulating AKT signaling to promote the proliferation and tumorigenicity of endometrial cancer cells." (PMID 30787270, 2019).
lung squamous cell carcinoma (7 papers, 2020 to 2025). "In lung squamous cell carcinoma, YTHDF2 is significantly negatively associated with PD-L1 and PD-L2." (PMID 36479088, 2022). "Reduced EMT was observed in YTHDF2-deleted Hela cells, and overexpression of YTHDF2 enhanced EMT in lung squamous cell carcinoma cells." (PMID 40100806, 2025). "Clinically, immunohistochemical staining revealed the relationship between YTHDF2 expression levels and the clinicopathological characteristics of lung squamous cell carcinoma patients." (PMID 34996459, 2022). "In the immunohistochemical staining results, YTHDF2 protein expression levels in lung squamous cell carcinoma tissues were markedly higher than those in the corresponding normal lung tissues." (PMID 34996459, 2022). "In brief, the results highlight high-YTHDF2 expression predicted a worse prognosis of LUSC, while hypoxia-mediated YTHDF2 overexpression promotes lung squamous cell carcinoma progression by activation of the mTOR/AKT signaling pathway." (PMID 34996459, 2022). "In this study, we further explored the expression level and biological role of YTHDF2 in lung squamous cell cancer." (PMID 34996459, 2022). "Our data showed that YTHDF2 was mediated by hypoxia exposure and orchestrated proliferation and invasion in lung squamous cell cancer." (PMID 34996459, 2022). "However, the function of YTHDF2 in lung squamous cell carcinoma (LUSC) remains elusive." (PMID 34996459, 2022). "In lung squamous cell carcinoma, there was no immune-related gene set related to YTHDF2." (PMID 36479088, 2022).